PIMREG (PICALM interacting mitotic regulator)
Description:
During mitosis, may play a role in the control of metaphase- to-anaphase transition.
Synonyms: CATS; FAM64A; RCS1; FLJ10156; FLJ10491
Tractability: PROTAC: UniProt records ubiquitination sites on it; ubiquitination databases record sites on it.
Gene: Protein-coding gene on chromosome 17 (6,443,807 to 6,451,469, forward strand). Ensembl gene ENSG00000129195.
Subcellular location: Nucleus; Nucleus, nucleolus
Subcellular location (Human Protein Atlas): Nucleoplasm
Gene Ontology:
Molecular function: protein binding
Cellular component: nucleolus; nucleoplasm; nucleus
Genetic constraint (gnomAD): Loss-of-function variants: 19 observed, 24.59 expected, observed/expected ratio (o/e) 0.77, 90% interval 0.54 to 1.13. The upper end of that interval is the gene's LOEUF score, 1.13, which puts it in group 4 of 6, group 1 being the genes least tolerant of losing a copy. Missense variants: 283 observed, 319.1 expected, observed/expected ratio (o/e) 0.89, 90% interval 0.8 to 0.98. Synonymous variants: 112 observed, 130.08 expected, observed/expected ratio (o/e) 0.86, 90% interval 0.74 to 1.01.
Homologues: Orthologues: chimpanzee PIMREG (93% identical), macaque PIMREG (89% identical), pig PIMREG (77% identical), mouse Pimreg (73% identical), dog PIMREG (71% identical), rat Pimregl1 (71% identical), rabbit PIMREG (71% identical), rat Pimregl1 (68% identical), tropical clawed frog pimreg (29% identical).
Diseases named in the same sentence as PIMREG in open-access papers:
PIMREG is named in the same sentence as 116 diseases in open-access papers, as found by Europe PMC text mining. Sharing a sentence is not in itself a finding about the gene and the disease. The quoted sentences say what the papers report.
breast carcinoma (16 papers, 2013 to 2026). "Further studies are needed to explore the potential interactions between PIMREG and immune checkpoints in breast cancer." (PMID 37483962, 2023). "Previous studies have reported that the knockdown of PIMREG can inhibit the proliferation of prostate cancer, glioma and breast cancer cells by prolonging G1 cell phase." (PMID 36776322, 2023). "Our findings align with previous literature, highlighting the crucial role of PIMREG in promoting the formation of breast cancer cells." (PMID 37483962, 2023). "Recent studies have found that the upregulation of PIMREG expression is related to the poor prognosis of breast cancer, neuroblastoma, cholangiocarcinoma, osteosarcoma, glioma, prostate cancer and other cancers." (PMID 36776322, 2023). "Overall, these results indicate that PIMREG is likely overexpressed in breast cancer." (PMID 37483962, 2023). "PICALM interacting mitotic regulator (PIMREG) could promote breast cancer aggressiveness via sustaining nuclear factor (NF)-κB activation." (PMID 32849806, 2020). "The poor prognosis associated with PIMREG overexpression may be attributed to excessive NF- κB signaling, inhibition of the negative feedback loop, epithelial-to-mesenchymal transition (EMT), and enhanced breast cancer stemness." (PMID 37483962, 2023). "Moreover, PIMREG was verified to promote breast cancer (BRCA) aggressiveness through activation of the NF-κB pathway, suggesting that it may be a novel prognostic indicator for BBCA." (PMID 34594356, 2021). "Next, we investigated whether expression levels of PIMREG, CEP55, and MTFR2 is related to the expressions of BCSC markers in breast cancer cell lines." (PMID 33718103, 2020).
glioblastoma (8 papers, 2011 to 2024). The most malignant astrocytic tumor (WHO grade IV). "Our results showed that PIMREG was overexpressed in many tumor types, including bladder urothelial carcinoma, bone cancer, cholangiocarcinoma, and glioblastoma multiforme." (PMID 34268011, 2021). "In addition, PIMREG expression correlated with glioma histology, for example, low expression in oligodendroglioma and astrocytoma and high expression in glioblastoma and secondary glioblastoma." (PMID 35928818, 2022).
leukemia (7 papers, 2014 to 2025). A malignant (clonal) hematologic disorder, involving hematopoietic stem cells and characterized by the presence of primitive or atypical myeloid or lymphoid cells in the bone marrow and the blood. "Interestingly, lower expression of PIMREG was also observed in cancer datasets, including brain and CNS, leukemia, and lung cancers." (PMID 34594356, 2021). "Moreover, a previous study claimed that PIMREG expressed highly protein levels in cancer cells such as lymphoma and leukemia, but hardly expressed in lymphocytes from peripheral blood or non-proliferative T cells." (PMID 34594356, 2021). "We discovered that PIMREG expression was markedly increased in most cancer types, including bladder, brain and central nervous system (CNS), breast, cervical, colorectal, esophageal, gastric, head and neck, leukemia, lung, melanoma, ovarian prostate, pancreatic, prostate, sarcoma and other cancers." (PMID 34594356, 2021).
pancreatic cancer (7 papers, 2019 to 2025). "PIMREG is known to positively regulate STAT3 activity to promote cell differentiation and shown to be associated with poor survival in the BC and pancreatic cancer." (PMID 33718103, 2020).
colitis (5 papers, 2012 to 2022). Inflammation of the colon. "A previous study has suggested that PIMREG regulates Th17 differentiation and colitis and inflammation-associated cancer by modulating transcriptional activity of STAT3, indicating that PIMREG may be correlated with immune response in the tumorigenesis." (PMID 34594356, 2021).
glioma (5 papers, 2014 to 2024). A benign or malignant brain and spinal cord tumor that arises from glial cells (astrocytes, oligodendrocytes, ependymal cells). "We found that PIMREG expression was upregulated in gliomas and positively associated with WHO grade." (PMID 35928818, 2022). "In conclusion, PIMREG overexpression in gliomas is associated with poor prognosis of patients with glioma and is related to immune cell infiltrates and the responses to immunotherapy." (PMID 35928818, 2022). "In our study, we revealed a relationship between PIMREG expression in gliomas and the infiltration of some TIICs." (PMID 35928818, 2022). "The present study was designed to explore the expression of PIMREG in glioma and its relevance to the clinicopathological features and prognosis of glioma patients." (PMID 35928818, 2022). "In this work, we found that PIMREG expression was upregulated in gliomas compared with normal brain tissues and increased with WHO grade." (PMID 35928818, 2022). "The results of three datasets obtained from the GEO database, GSE16011 (P = 9.4e-06), GSE14805 (P = 3.4e-05), and GSE19728 (P = 0.00033), demonstrated that PIMREG expression was upregulated in gliomas compared to normal brain tissues." (PMID 35928818, 2022). "Univariate Cox regression illustrated that PIMREG expression, WHO stage, 1p/19q codeletion, age and IDH status were associated with the prognosis of glioma." (PMID 35928818, 2022). "We further performed experiments in vitro to verify the role of PIMREG in glioma cells." (PMID 35928818, 2022). "In conclusion, PIMREG was highly expressed in gliomas and correlated with WHO classification." (PMID 35928818, 2022). "In addition, we analyzed the relationship of PIMREG with these immune checkpoint genes in gliomas through the GEPIA 2.0 database." (PMID 35928818, 2022). "In conclusion, there is a relationship between PIMREG expression and patient prognosis, which may be a predictor of prognosis in glioma patients." (PMID 35928818, 2022). "The transwell assay indicated that PIMREG knockdown inhibited the invasion of U251 and U87MG glioma cells." (PMID 35928818, 2022). "Glioma patients who had high expression of PIMREG showed poorer OS (P < 0.0001) and DFS (P = 5.4e-14) than those with low expression of PIMREG." (PMID 35928818, 2022). "However, the oncogenic role of PIMREG in glioma has not been fully explored." (PMID 35928818, 2022).
infiltrating ductal carcinoma (1 paper, 2023). "Additionally, PIMREG expression was significantly higher in infiltrating ductal carcinoma compared to infiltrating lobular carcinoma (P < 0.001)." (PMID 37483962, 2023). "Further analysis of subgroups found that the upregulation of PIMREG was associated with worse OS in infiltrating lobular carcinoma with HR of 2.79 (95%CI [1.13–6.75]; P = 0.026), but not in infiltrating ductal carcinoma." (PMID 37483962, 2023).
renal carcinoma (1 paper, 2023). A carcinoma arising from the epithelium of the renal parenchyma or the renal pelvis. "Subsequently, we analyzed the expression level of PIMREG in 539 renal cancer tissues and 72 normal renal tissues in TCGA database." (PMID 36776322, 2023).
tumor (28 papers, 2010 to 2026). "This work also discovered that the expression of PIMREG was associated with the stage of tumor in most tumors, and was especially different in stage I and IV cancers." (PMID 34594356, 2021). "All these findings suggest that the expression of PIMREG closely associated with the immune infiltration of tumor cells, affecting the prognosis and providing a new target for the improvement of immunotherapy for various types of cancer patients." (PMID 34594356, 2021). "We found that in each and every subgroup stratified by age, sex, and anatomic neoplasm subdivision, the high expression of PIMREG continued to lead to poor survival." (PMID 34268011, 2021). "In conclusion, our first pan-cancer analysis of PIMREG shows the presence of high expression of this gene in most tumor tissues compared to normal tissues and revealed a correlation of PIMREG expression with clinical prognosis." (PMID 34594356, 2021). "In particular, PIMREG was shown to play a vital role in the enhancement of tumorigenesis and progression of neoplasms in multiple cancer types." (PMID 34268011, 2021). "We observed a significant relationship between the expression of PIMREG and clinicopathological parameters, such as T stage, N stage, pathologic stage, sex, smoking, tumor status, number of packs smoked per year, and age." (PMID 34268011, 2021). "Patients with a high level of PIMREG were more likely to be presented with the disease in a late pathological stage, suggesting PIMREG as a tumor-related gene in LUAD." (PMID 34268011, 2021). "In this study, we found that the PIMREG gene was overexpressed in tumor compared with normal and adjacent normal tissues, and this overexpression was linked to worse OS, DSS and PFI." (PMID 34268011, 2021). "PIMREG has been identified in a recent study as a potential target gene necessary for effective immune targeting in tumor stem cell populations of BRCA." (PMID 34594356, 2021). "We then analyzed the expression of PIMREG in paired tumor and adjacent samples." (PMID 34268011, 2021). "In addition, we further found that the high expression of PIMREG continued to lead to poor survival even when patients where stratified according to age, sex, and anatomic neoplasm subdivision." (PMID 34268011, 2021). "The results suggest that PIMREG may act as an independent prognostic factor in a number of cancers, and that its high expression levels in major tumors are associated with poor prognostic outcomes, but further investigation of the specific role of PIMREG in each tumor is still needed." (PMID 34594356, 2021). "The results identified that the mRNA expression level of PIMREG in tumor tissues was significantly higher than adjacent normal tissues." (PMID 36776322, 2023). "In our study, we found that the expression of PIMREG was negatively correlated with T cells, macrophages, B cells, DCs and CD8+ T cells in LUAD, indicating that PIMREG might plays a significant role in regulating the tumor immune microenvironment." (PMID 34268011, 2021).
cancer (27 papers, 2011 to 2026). A tumor composed of atypical neoplastic, often pleomorphic cells that invade other tissues. "Also, elevated PIMREG expression is associated with a worse prognosis among patients with lung, liver, pancreatic, and other types of cancer." (PMID 37483962, 2023). "Furthermore, GSEA revealed that the high level of PIMREG might be linked to cancer-promoting pathways." (PMID 34268011, 2021). "Numerous studies have shown that the expression of PIMREG is closely related to the progression of malignant tumors." (PMID 36776322, 2023). "Phosphatidylinositol binding clathrin assembly protein interacting mitotic regulator (PIMREG) expression is upregulated in a variety of cancers." (PMID 37483962, 2023). "Recent studies revealed that PIMREG is upregulated in many different types of cancer, such as prostate cancer, lung cancer, gastric cancer, esophageal cancer, colorectal cancer, and most importantly, BC." (PMID 37483962, 2023). "In these types of cancer, PIMREG was found to express generally higher in male patients compared to female, but the involved mechanisms need to be further elucidated." (PMID 34594356, 2021). "We found that the different expression levels of PIMREG only occurred in patients with 5 types cancers, including BLCA, HNSC, KIRC, DLBC, LUAD." (PMID 34594356, 2021). "Our study extracted datasets from several databases such as HPA, Oncomine, TGCA and CCLE to investigated the PIMREG expression levels and its correlation with prognosis and immune response in various cancers." (PMID 34594356, 2021). "We next investigated the differences in PIMREG expression between the male and female patients with 27 types cancers (except BRCA, CESC, UCEC, OV, PRAD, TGCT, and UCS)." (PMID 34594356, 2021). "The results showed that the infiltrating levels of immune cells correlated significantly with the expression of PIMREG in most cancer types." (PMID 34594356, 2021). "This work showed that the PIMREG gene was highly expressed in 20 cancers, and IHC results confirmed this trend at protein level." (PMID 34594356, 2021). "The present work indicated that the expression of PIMREG associated with TMB in 24 cancers and with MSI in 10 cancers." (PMID 34594356, 2021). "To evaluate the level of expression of PIMREG in various cancers, we performed a systematic analysis using data downloaded from TCGA databases." (PMID 34268011, 2021). "Our findings indicate that PIMREG is highly expressed in at least 24 types of cancer, and is negatively correlated with prognosis in major cancer types." (PMID 34594356, 2021). "Our study revealed a promising potential for CSC-target immunotherapy in the early stage of cancer and a probable value for PIMREG and MTFR2 as biomarkers and targets for immunotherapy." (PMID 33718103, 2020). "Afterward, we discovered that PIMREG expression correlated with age in some cancers." (PMID 34594356, 2021). "Our results showed that PIMREG plays a crucial role in cancer immunity." (PMID 34594356, 2021). "Additionally, we found that the expression of PIMREG correlated to gender in some cancer types, including BLCA, DLBC, HNSC, KIRC, and LUAD." (PMID 34594356, 2021). "In addition, immune activation genes and immunosuppressive genes were co-expressed with PIMREG in all cancer types, while the correlation in ACC, UCS, and UVM were relatively small." (PMID 34594356, 2021). "We used Oncomine to investigate PIMREG expression levels in normal and various cancer tissues." (PMID 34594356, 2021). "It has been shown that PIMREG controls the transition from metaphase to anaphase of the cell’s mitotic cycle, so it could be a marker for the proliferation and tumorigenesis of various cancer kinds." (PMID 37483962, 2023). "Hence, high expression of PIMREG in certain cancers leads to a decline in immune scores, which may lead to rapid development of cancer cells." (PMID 34594356, 2021). "In addition, PIMREG expression was correlated with TMB in 24 cancers and with MSI in 10 cancers." (PMID 34594356, 2021).
cancer (continued). "Hence, we hypothesized that it was the high expression of PIMREG in these patients with advanced cancer that leaded to a lower survival time." (PMID 34594356, 2021). "Hence, PIMREG is highly expressed in at least in 24 cancer types and high expression of PIMREG may be a predictive signal for tumorigenesis." (PMID 34594356, 2021). "Therefore, we speculate that PIMREG may play a role in cancer development by regulating immune system-related functions." (PMID 34594356, 2021). "In addition, PIMREG expression is correlated with TMB, MSI and the infiltration of immune cells in various cancers." (PMID 34594356, 2021). "We also found that the MHC genes had co-expression with PIMREG in almost all cancer types without READ and UVM, particularly in THCA, TGCT, UCEC, LUSC, LUAD, LIHC, LGG, and GBM." (PMID 34594356, 2021). "PIMREG and MTFR2 are considered as potential target genes in CSC population that are required for effective immune targeting, the pan-cancer analysis implies that these genes may also play important roles in other tumors." (PMID 33718103, 2020). "It was found that PIMREG, MTFR2, and CEP55 were overexpressed in BC and also in many other cancers." (PMID 33718103, 2020).
cardiac diseases (1 paper, 2023). "The consensus SDGs include novel as well as known genes in mouse heart development or cardiac diseases, such as PICALM interacting mitotic regulator (Fam64a), four and a half LIM domain protein 1 (Fhl1), and others." (PMID 37322439, 2023).
PIMREG also shares sentences with these, for which no sentence is quoted: atherosclerosis (6 papers); lung carcinoma (6); lymphoma (6); prostate carcinoma (6); rheumatoid arthritis (6); ovarian carcinoma (5); Autoimmunity (4); cardiovascular disease (4); diabetes (4); infection (4); lung disease (4); primary Sjögren syndrome (4); autoimmune disease (3); colorectal cancer (3); cystic fibrosis (3); emphysema (3); lung adenocarcinoma (3); melanoma (3); neurodegenerative disease (3); Obesity (3); osteosarcoma (3); periodontitis (3); psoriasis (3); systemic lupus erythematosus (3); triple-negative breast carcinoma (3); adenocarcinoma (2); Arthritis (2); asthma (2); astrocytoma (2); Bladder Carcinoma (2).
A further 75 diseases each share a sentence with PIMREG in 2 papers or fewer.